PPARA (peroxisome proliferator activated receptor alpha)
Diseases named in the same sentence as PPARA in open-access papers (continued):
Sharing a sentence is not in itself a finding about the gene and the disease.
Hepatic steatosis (continued). "The authors concluded that ASX treatment ameliorates high-fat diet-induced hepatic lipid accumulation and hepatic steatosis in mice via differential regulatory actions involving PPARα and PPARγ." (PMID 31018521, 2019). "While PPARα activation has been known to alleviate fatty liver by stimulating β-oxidation and reducing lipogenesis, the effect of activated PPARγ on hepatic steatosis is controversial." (PMID 30733541, 2019). "In mouse models, PPARα agonists reduced adiposity, decreased muscle and hepatic steatosis and consequently improved insulin sensitivity." (PMID 29454501, 2019). "In a previously identified study, it was found that the effect of 4-(benzo[d]thiazol-2-yl)benzene-1,3-diol (MHY553), a novel PPARα agonist, alleviated hepatic steatosis through an increase of fatty acid oxidation and a decrease in inflammation in aged rats." (PMID 30115876, 2018). "Previously, it was reported that a decrease in SIRT1 expression inhibits SREBP1 and lipogenesis, decreases PPARα levels which leads to the reduced use of fat as an energy source, and induces fat accumulation and hepatic steatosis." (PMID 30363947, 2018). "Knockout of PPARα in ob/ob mice results in hepatic steatosis, supporting a role of PPARα in the regulation of hepatic lipid metabolism." (PMID 29936596, 2018). "Animal studies further showed a positive effect of HIET (20 μg/kg BW, 8 weeks, daily) in regulating AMPK/SREBP/PPARα signaling pathways and reducing body weight gain, plasma lipid levels, and hepatic steatosis in high fat diet (HFD)-fed mice." (PMID 29968750, 2018). "Alcohol intake also causes an alcoholic fatty liver, which is induced by increased SREBP-1c and PPARγ2 expression and decreased PPARα expression." (PMID 30567368, 2018). "Our animal study also demonstrated a beneficial role of HIET in preventing the HFD-induced hepatic steatosis via regulating AMPK/SREBP/PPARα signaling pathway." (PMID 29968750, 2018). "Moreover, DAS-alone didn’t protects the INH/LPS-induced hepatic steatosis as evident by the massive accumulation of lipid droplets and elevated both serum and hepatic lipid parameters, which further associated with repressions of lipid profile regulators PPARα, FAS, and HMGCS." (PMID 29563874, 2018). "Under ER stress conditions, ATF6α knockout mice exhibited hepatic steatosis due to the inhibition of fatty acid β-oxidation, and was accompanied by reduced expression of the related genes, including PPARα, CPT1, CPT2 and ACOX1." (PMID 30081561, 2018). "Ethanol exposure reduces fatty acid oxidation by downregulating PPARα, an important transcription factor for the expression of fatty acid oxidation genes, which leads to the development of hepatic steatosis." (PMID 30200508, 2018). "Combining all, this study demonstrates the positive effect of HIET on reducing hepatic steatosis via regulating AMPK/SREBP/PPARα signaling pathway." (PMID 29968750, 2018). "This response was less pronounced in PPARα knockout animals and coincided with hepatic steatosis, again emphasizing the critical role of PPARα in promoting FAO and preventing hepatic lipid accumulation." (PMID 29936596, 2018). "During this process, we unexpectedly discovered that MG treatment promoted the expression of PPARα in OA-induced hepatic steatosis and Ty-stimulated hyperlipidemia." (PMID 29467759, 2018). "In both animal models, treatment with a PPARα agonist improved hepatic steatosis, inflammation, and, in the case of methionine/choline deficiency, fibrosis." (PMID 28159867, 2017). "This cell model was qualified as an in vitro hepatic steatosis model for further silent RNA assay to knockdown of PPARα and PPARγ." (PMID 28831172, 2017). "Conversely, treatment of mice fed a HFD with a PPARα agonist have reduced hepatic steatosis and inflammation, further highlighting the critical role for PPARα in hepatic fatty acid catabolism." (PMID 28159867, 2017).
Hepatic steatosis (continued). "In contrast to its expression loss during steatogenesis, circRNA_0046367 normalization abolishes the miR-34a-induced PPARα inhibition and hepatic steatosis." (PMID 29018509, 2017). "Fibrates act as agonists for PPARα, which serves as a sensor for xenobiotic compounds and exogenous and endogenous lipids to regulate energy consumption, hepatic steatosis, lipoprotein synthesis, inflammation, and development of liver cancer." (PMID 28401920, 2017). "Silencing of miR-34a using a miR-34a inhibitor was shown to prevent liver injury and improve hepatic steatosis through its target proteins, like PPARα and SIRT1, which can activate AMP-activated protein kinase in an animal model of NAFLD." (PMID 28250026, 2017). "Our study evidenced an important clue that pioglitazone attenuated hepatic steatosis by amplifying cytosolic lipolysis, β-oxidation, and lipophagy, which were differentially mediated by both PPARα and PPARγ." (PMID 28831172, 2017). "Pioglitazone, exhibiting dual PPARα/PPARγ agonist, has been established to improve insulin sensitivity and attenuate hepatic steatosis in human studies." (PMID 28831172, 2017). "Although a critical role for PPARα in fatty acid catabolism has been well established, several studies have reported increased hepatic steatosis upon PPARα activation." (PMID 28159867, 2017). "In conclusion, MHY553 is a novel PPARα agonist that improved aged-induced hepatic steatosis, in part by increasing β-oxidation signaling and decreasing inflammation in the liver." (PMID 28545035, 2017). "MMP inhibitors have been shown to protect mice from HFD-induced fatty liver and shown to increase Pparα gene expression." (PMID 28740132, 2017). "Pparα-/- mice display increased hepatic steatosis, oxidative stress, and inflammation when fed a high fat diet but not on normal chow." (PMID 27611931, 2016). "PPARα-null mice showed inhibition of fatty acid oxidation and displayed severe hepatic steatosis when animals were challenged with an HFD or fasting." (PMID 27189661, 2016). "A protective role for PPARα against liver steatosis and inflammation in NASH has been suggested by the increased susceptibility to NASH of PPARα knockout mice." (PMID 28003852, 2016). "Results have shown that the expression of PPARα is downregulated in liver steatosis, thereby favoring lipogenesis during oxidation." (PMID 25751727, 2015). "PPARα activators, such as the widely prescribed fibrate drugs, ameliorate hepatic steatosis through enhancing mitochondrial FAO in mice." (PMID 26330104, 2015). "Additional studies are planned to further delineate the mechanisms by which NDGA improves HFrd-induced hypertriglyceridemia and hepatic steatosis via increased expression of PPARα and activation of AMPK." (PMID 26394137, 2015). "Our results show that both PPARδ and PPARα receptors are essential for GW501516-driven adipose tissue reduction and subsequently hepatic steatosis, with PPARα working downstream of PPARδ." (PMID 26604919, 2015). "In animal models, inefficient PPARα sensing (characteristic for PPARα_/_ mice) enables the oxidation of the influxed fatty acids and leads to severe hepatic steatosis development." (PMID 24524207, 2014). "In the present study, we focused on exploring the effect and mechanism of PPARα activation on hepatic triglyceride accumulation and hepatic steatosis." (PMID 24926685, 2014). "Using a series of in vivo and in vitro experiments, we confirmed that PPARα activation through fenofibrate increased liver triglyceride synthesis, leading to hepatic steatosis." (PMID 24926685, 2014).
Hepatic steatosis (continued). "PPARα also showed coordinated regulation with PGC1α in hepatic steatosis, which was demonstrated by the enhanced beneficial effects of clofibric acid, a PPARα agonist, on fatty acid accumulation in PDK4 knockout mice." (PMID 24520982, 2014). "In our study, we observed that the PPARα KO mice had exacerbated hepatic steatosis and liver inflammation after 12 weeks of exposure to a HFD." (PMID 25147439, 2014). "In conclusion, the results of the present study showed that PPARα activation through fenofibrate treatment increased liver triglyceride synthesis, leading to hepatic steatosis." (PMID 24926685, 2014). "Our finding of the significant beneficial effect of ERC on hepatic steatosis can be explained by an increase of PPARα DNA binding activity in liver." (PMID 24444255, 2014). "For this, wild-type and PPARα-knockout mice were fed a high-fat diet, either untreated or treated with palmitoleic acid, and evaluated for hepatic steatosis and inflammation and whole body glucose homeostasis." (PMID 25147439, 2014). "Taken together, these findings indicate the molecular mechanism by which PPARα activation increases liver triglyceride accumulation and suggest an adverse effect of fibrates on the pathogenesis of hepatic steatosis." (PMID 24926685, 2014). "Hepatic deletion of SIRT1 impairs PPARα activity, decreases fatty acids oxidation, and results in hepatic steatosis and inflammation in response to high-fat feeding." (PMID 24759758, 2014). "SBS possesses a repressive property on hepatic steatosis, which is associated with inhibition of SREBP1c, PPARγ, ACC, DGAT2, and FAS, and induction of PPARα, suggesting a potential application of SBS in treatment of HFD-induced NAFLD." (PMID 24905748, 2014). "Administration of tart cherries as medicinal food rich in anthocyanins was accompanied with decrease in hyperlipidemia, hyperinsulinemia, fatty liver and hepatic steatosis through enhanced hepatic PPARα and some target genes including acyl-coenzyme A oxidase." (PMID 23938049, 2013). "Overall, the current study reports enhanced Nrf2 activity, genetically via Keap1-KD, prevented fasting-induced fatty liver by inhibiting fatty acid transport and impairing activation of the Pparα signaling pathway in liver." (PMID 24224011, 2013). "Activation of PPARα that is in particular highly expressed in liver, is a well-established strategy for treating metabolic diseases including fatty liver, which can systemically also have beneficial effects on insulin sensitivity." (PMID 24265809, 2013). "Deletion of PPARα in apoE2-KI mice fed a Western diet also aggravates liver steatosis and inflammation development." (PMID 23024649, 2012). "It is well established that PPARα is a central regulator for hepatic glucose and lipid metabolism as well as the development of lipid disorders including hepatic steatosis and NAFLD." (PMID 22110479, 2012). "By contrast, in conditions in which PPARα function and/or expression is altered such as hepatic steatosis, and small-size liver grafts, FA metabolism is deviated toward the accumulation of inadequately metabolized fat, favoring ROS generation." (PMID 22675337, 2012). "Activation of PPARα by the agonist Wy-14,643 ameliorated alcoholic fatty liver- and MCD-induced steatohepatitis." (PMID 22675337, 2012). "Activation of PPARα by WY14643 ameliorated hepatic steatosis through increasing lipids oxidation promoting genes CYP4A10, CYP4A14, FGF21, adiponectin, SIRT1 and PGC-1α expression, and suppressing fatty acid synthesis promoting genes FAS and PI3K expression." (PMID 22208561, 2011). "Given the beneficial effects of PPARα agonists on liver steatosis and inflammation, it is possible that the beneficial effects of KO in this case are due to its stimulatory action on this compound." (PMID 21749725, 2011).
Hepatic steatosis (continued). "Administration of PPARα agonists, such as the widely prescribed fibrate drugs clofibrate, gemfibrozil, and fenofibrate, ameliorate hyperlipidemia in humans and hepatic steatosis in mice." (PMID 20487553, 2010). "Conversely, treatment with PPARα agonists lowers hepatic triglyceride levels in models of hepatic steatosis and can prevent the fasting-induced increase in liver TG." (PMID 20936127, 2010). "The crucial role of PPARα in mitochondrial fatty acid oxidation is illustrated by the phenotype of fasted PPARα−/− mice, which exhibit hypoketonemia, hepatic steatosis, and elevated plasma free fatty acid levels." (PMID 20936127, 2010). "The increased expression of the PPARα-dependent peroxisomal β-oxidation pathway induced in hepatic steatosis provides an alternative mechanism to remove excessive fatty acids." (PMID 20300478, 2009). "Conversely, treatmentwith PPARα agonists lowershepatic triglyceride levels in various models of hepatic steatosis." (PMID 18288265, 2007). "Key genes such as CPT1A and PPARα may be potential targets, given their reported modulation by polyphenols in similar hepatic steatosis models." (PMID 41575476, 2026). "Conversely, selective hepatic vagotomy results in exacerbation of steatohepatitis, with increased inflammatory cytokine expression, and a concomitant decrease in peroxisome proliferator-activated receptor alpha (PPARα) activity leading to the aggravation of liver steatosis." (PMID 41424854, 2026). "We first asked if PPARα overexpression alone is enough to reduce fatty liver disease." (PMID 40618957, 2026). "Since WY-14643 (Pirinixic acid) is a well established and highly selective PPARα agonist, treatment with WY-14643 could prevent hepatic steatosis during ethanol ingestion." (PMID 40263984, 2025). "Furthermore, in animal models, Pb impairs lipid homeostasis genes like PPARα, inducing hepatic steatosis." (PMID 40687133, 2025). "Additionally, the circRNA_0046367/miR-34a/PPARα regulatory system is disrupted in hepatic steatosis, with elevated miR-34a inhibiting PPARα, a key lipid metabolism regulator." (PMID 40668532, 2025). "In contrast, knockout of PPARα in mice results in hepatic steatosis." (PMID 39911797, 2025). "Echinacoside can alleviate hepatic steatosis by upregulating PPARα." (PMID 41154556, 2025). "The purpose of this study was to determine whether aerobic exercise may improve liver steatosis by adjusting the miR-34a-PPARα/SIRT1 signal pathway." (PMID 41223206, 2025). "In a word, PPARα/SIRT1-AMPK pathway was involved in miR-34a-regulated hepatic steatosis." (PMID 41223206, 2025). "Given that fatty acids serve as natural ligands for Pparα activation, lipolytic flux in BAP31-deficient models may further attenuate Pparα signaling and worsen hepatic steatosis." (PMID 41465598, 2025). "Furthermore, it was reported that treatment with PPARα agonist WY-14643 induces peroxisomal fatty acid oxidation and inhibits ethanol-induced hepatic steatosis in mice." (PMID 40263984, 2025). "The regulatory role of miR-34a-PPARα/SIRT1 in liver steatosis was summarized in." (PMID 41223206, 2025). "Study of the mechanism revealed that the HLF/PPARα axis regulated gut microbiota‐derived extracellular vesicles (fEVs); which, through the gut‐liver cycle, suppressed hepatocyte ferroptosis and reduced hepatic steatosis." (PMID 40236774, 2025). "Germline, whole-body GLUT8-deficient mice, and mice treated with GLUT8 gene-silencing oligonucleotides exhibit increased calorie expenditure, increased hepatocyte fasting-like signaling through the PPARα pathway, and protection from hepatic steatosis in diet-induced obese models." (PMID 40982234, 2025). "Moreover, dietary MUFAs can activate PPARα, increasing lipid oxidation, and reducing resistance for insulin resulting in hepatic steatosis reduction." (PMID 41144456, 2025).
Hepatic steatosis (continued). "Decreased fatty acid content in BAP31-LKO mice reduced Pparα signaling activation and decreased fatty acid oxidation, leading to the reduction in lipid utilization in the liver, thus accelerating the progression of alcoholic fatty liver." (PMID 41465598, 2025). "ZFP30 is a member of the Krüppel-associated box zinc finger protein (KRAB-ZFP) family; recent studies have shown that chlorogenic acid inhibits the upregulation of ZFP30 in NAFLD and promotes the expression of PPARα, thereby enhancing FAs β-oxidation and alleviating hepatic steatosis." (PMID 41154556, 2025). "The results revealed that the proteins interacting with PGC-1β were enriched in pathways related to fatty liver disease and were involved in PPARA, thereby activating gene expression, the nuclear receptor transcription pathway, and the intracellular receptor signaling pathway." (PMID 41561171, 2025). "PPARα activity is known to be suppressed in fatty liver diseases." (PMID 40793786, 2025). "Thus, HFD-induced deSUMOylation of FoxA1 led to hepatic steatosis via inactivation of Sirt6/Pparα pathway." (PMID 39277582, 2024). "Furthermore, ω-3 polyunsaturated fatty acids (PUFAs) attenuate hepatic steatosis through upregulation of PPARα/CPT-1α signaling pathway." (PMID 38699583, 2024). "Our findings revealed that AMPK/ PGC-1α, PPARα-dependent autophagy pathways in the pathophysiology of IR and hepatic steatosis has been shown, suggesting that DHM might potentially serve as a promising treatment option for addressing this disease." (PMID 38532480, 2024). "Additionally, we observed a correlation between USP25 and PPARα protein levels, indicating the potential role of USP25 in modulating PPARα expression in hepatic steatosis." (PMID 39395794, 2024). "Similar to our findings, Zengpeng and colleagues demonstrated that dietary genistein supplementation resulted in the upregulation of gene transcription associated with fatty acid beta-oxidation, including PPARα, PPARδ, ACOT8, ACAD8, and ACADs in the liver of laying hens induced fatty liver." (PMID 38540097, 2024). "Furthermore, nuciferine improves hepatic steatosis by activating PPARα/PGC-1α pathway in diabetic mice." (PMID 38699583, 2024). "Interestingly, the upregulation of PPARα suggests that the fish's body is actively responding to counteract the effects of liver steatosis." (PMID 38644412, 2024). "Additionally, mTORC1, which suppresses Hmgcs2 expression and ketogenesis by inhibiting the transcriptional activity of PPARα, is frequently activated in fatty liver disease." (PMID 39403635, 2024). "Icariin, one of the bioactive components isolated from the medicinal plant Epimedium brevicornu Maxim, can ameliorate hepatic steatosis in female rats with polycystic ovary syndrome by upregulating the PPARα-mediated expression of FAO-related genes such as CPT1α." (PMID 38668346, 2024). "Interestingly, the expression levels of hepatic steatosis-related genes, such as LXRα, C/EBPα, PPARα, ACC, ACOX1, and CPT-1, were markedly decreased in the D-Gal and melatonin cotreated group." (PMID 37886973, 2023). "In the liver, PPARα regulates lipid metabolism and controls liver homeostasis, and dysregulation and overexpression of PPARα may lead to hepatic steatosis, steatohepatitis, steatofibrosis, and liver cancer." (PMID 36980601, 2023). "In this respect, a prior study has revealed a tight association between circRNAs with hepatic steatosis and NASH and circRNA_0046367 has been found to prevent hepatic steatosis by reversing the inhibitory effect of miR-34a on PPARα by blocking miRNA/mRNA interaction with MRE." (PMID 37190114, 2023). "We hypothesized that VD may attenuate hepatic steatosis via the PPARα pathway and that these effects may be inhibited by MK886 in a NAFLD rat model and oleic acid (OA)-induced HepG2 cells." (PMID 37033263, 2023).